APOA2 (apolipoprotein A2)
Diseases named in the same sentence as APOA2 in open-access papers (continued):
Sharing a sentence is not in itself a finding about the gene and the disease.
pancreatic cancer (continued). "While apoA2‐AT and apoA2‐TQ concentrations exist in a certain balance in healthy individuals, it was found that in pancreatic cancer patients, there is a group of cases with low apoA2‐AT and high apoA2‐TQ concentrations and a group of cases with high apoA2‐AT and low apoA2‐TQ concentrations." (PMID 40895517, 2026). "EV-derivedapolipoproteins may also make good biomarkers for the early detectionof pancreatic cancer, as a clinical study of a blood biomarker composedof apolipoprotein A2 isoforms has shown promising results." (PMID 40720603, 2025). "Apolipoprotein A2-ATQ/AT (apoA2-ATQ/AT) is a new biomarker for diagnosing pancreatic cancer (PC)." (PMID 39272705, 2024). "Previous studies have suggested that APOA2 might serve as a biomarker for diseases such as Alzheimer’s disease and pancreatic cancer." (PMID 36192674, 2022). "Individual serum markers may also be useful as predictors of cancer development; for example, apoA2 may detect pancreatic cancer at an early stage." (PMID 31936330, 2020). "It has been recently demonstrated, by plasma analysis of European EPIC cohort patients, that the combination CA19-9 and ApoA2 may improve detection of pancreatic cancer compared to CA19-9 alone." (PMID 32411709, 2020). "We found that the combined analysis of CA19-9 and apoA2-ATQ/AT could lead to the detection of pancreatic cancer up to 18 months prior to diagnosis under usual care compared to an analysis of CA19-9 alone." (PMID 32707720, 2020). "Additionally, a prospective evaluation was conducted to measure CA19-9 and apoA2-ATQ/AT levels in 156 patients with pancreatic cancer and 217 matched controls within the European Prospective Investigation into Cancer and Nutrition (EPIC) study." (PMID 32707720, 2020). "To confirm the diagnostic accuracy of apoA2-ATQ/AT, we prospectively collected plasma samples of healthy controls, of PDAC, and of the risk diseases of pancreatic cancer and other gastroenterological malignancies from seven independent medical institutions in Japan (n = 833)." (PMID 27673558, 2016). "Apolipoprotein A-II (APOA2) was proposed as a potential marker for urinary bladder and pancreatic cancer." (PMID 39201484, 2024). "In this study, the ELST‐blue score had a significant negative correlation with the apoA2‐i Index, which has been reported as a biomarker of pancreatic cancer." (PMID 40895517, 2026). "However, although slight reductions in apoA2-ATQ/AT were detected in other gastroenterological tumors but not in pancreatic cancer, interestingly, hyper- and hypo-processing patterns were never observed in other gastroenterological diseases." (PMID 27673558, 2016). "Reduced serum levels of apoA2 isoforms, especially apoA2-ATQ/AT and reduced specific apoA2 isoform hypo-processing patterns, have been proposed as useful in differentiating disease activity in AIP and could aid the differentiation between AIP and pancreatic cancer." (PMID 35884816, 2022). "Apolipoprotein A2 (APOA2), which is not directly produced by tumors, may help detect pancreatic cancer through mechanisms distinct from carbohydrate antigen 19-9 (CA 19-9)." (PMID 40227633, 2025).
amyloidosis (21 papers, 2008 to 2026). A disorder characterized by the localized or diffuse accumulation of amyloid protein in various anatomic sites. "According to GeneCards, diseases associated with APOA2 proteins, encoded by genes Apoa2, include hypercholesterolemia and some types of amyloidosis." (PMID 39062058, 2024). "This suggests that APOA4 and APOA2 are inextricably linked and that differentiating APOA4 amyloidosis from APOA2 amyloidosis is difficult." (PMID 39699959, 2024). "While age-related APOA2 amyloidosis has been reported in aged mice — and is characterized by amyloid deposits, especially in the intestines — only minor amyloid deposits were observed in the intestines." (PMID 39699959, 2024). "Recent studies reported that proteome profiles of amyloid deposits in individuals with APOA4 amyloidosis demonstrated the presence of APOA2 and vice versa." (PMID 39699959, 2024). "However, there is a possibility that structural changes in AA amyloid fibrils of Apoa2−/− mice could affect amyloid deposition, and will be the topic of future amyloidosis research." (PMID 29618729, 2018). "Apolipoprotein A2 (APOA2), the second most abundant apolipoprotein in HDL plays an important role in lipid metabolism but is involved in a variety of other processes such as plasma glucose homeostasis, amyloidosis and cancer." (PMID 37893070, 2023). "The expression levels of Apoa1 and Apoa2 mRNA did not change after CR treatment and amyloidosis induction." (PMID 28225824, 2017).
COVID-19 (18 papers, 2021 to 2025). A disease caused by infection with severe acute respiratory syndrome coronavirus 2. "The deficiency in apolipoproteins levels in COVID-19 compared to normal human plasma (NHP) and ICU-ARDS patients was most pronounced for APOA1, APOA2, APOA4, APOC3 and APOE." (PMID 37031181, 2023). "From these proteins CRTAC1, IGLV3-1, HRG, HSPB1, LCP1, ITIH3, and APOA2 have all been identified as correlating with COVID-19 in other research, but to our knowledge, the rest are novel." (PMID 37308820, 2023). "Decrements in total cholesterol (TC), TC-high-density lipoprotein (HDL), TC-low-density lipoprotein (LDL), apolipoprotein A2 (ApoA2), ApoD, and ApoM were reported in COVID-19 patients." (PMID 37587394, 2023). "Apolipoproteins APOA1, APOA2, APOL1, and APOM, which have been previously reported to be associated with macrophage and decreased in COVID-19 patients, were all downregulated in the CSF from the eight COVID-19 patients." (PMID 34956212, 2021). "Interestingly, lower levels of cholesterol and apolipoprotein A2 as well as in the HDL-bound form were found in CS patients compared with COVID-19." (PMID 34938772, 2021). "For example, Apolipoprotein A-II (APOA2), a key component of high-density lipoprotein (HDL), has been reported to be dysregulated in patients with COVID-19, reflecting alterations in lipid metabolism and the host inflammatory response." (PMID 41430040, 2025). "The apolipoproteins APOA1, APOA2 and APOA4 showed a 30% to 90% decline in COVID-19 and/or ICU-ARDS observation frequency compared to Normals (NHP)." (PMID 37031181, 2023). "Regarding the lipoprotein panel, for the main parameters the COVID-19 group is characterized by a significant increment of total TG and a decrement of total Chol, HDL-Chol, LDL-Chol, as well as of ApoA1 and ApoA2." (PMID 37943960, 2023). "Pathways depicting cholesterol, HDL and LDL metabolism (WP430, WP5109, WP4522, WP3601) are also among the top 10 pathways that have reduced activity in COVID-19 patients with significant reductions in APOA1, APOA2, APOC2, APOC3, APOB protein abundance." (PMID 36189295, 2022). "Although the cholesterol metabolism pathway was significantly downregulated (including APOA2, APOC1, APOH, CETP, and APOA4), the increased levels of PCSK9 and APOB suggested the dysregulation of cholesterol metabolism in severe and critical COVID-19 patients." (PMID 35958562, 2022). "Specifically, this includes smaller-sized VLDL fractions (VLDL-2, 3, and -4) and IDL-bound lipids in cholesterol, triglycerides, and phospholipids, as well as ApoA2 and nearly all HDL ApoA2 fractions, which were different between COVID-19 and CS samples." (PMID 34938772, 2021). "Apolipoprotein A2 and ApoA2 bound to large-sized HDL were significantly different in COVID-19 patients compared with CS." (PMID 34938772, 2021). "In particular, the COVID-19 group is characterized by a general increment of triglycerides (TG), and a decrement of phospholipids (Ph), total cholesterol (Chol), HDL- and LDL-cholesterol, as well as of apolipoprotein A1 and A2 (ApoA1 and ApoA2)." (PMID 35446921, 2022). "Interestingly, for cholesterol, total apolipoprotein A2, and apolipoprotein A2 bound to HDL, stronger effects were observed for CS patients in comparison with COVID-19 and HCs." (PMID 34938772, 2021). "Remarkably, in the present study, APOA2 levels were also reduced in critical patients compared to mild ones, which is in agreement with the findings of a systematic review reporting that adequate levels of APOA1 were related to a protection against mortality in patients hospitalized for COVID-19." (PMID 37371071, 2023). "In particularwe observed a decrease in the HDL components APOA4 and APOC1 in both COVID-19 non-ICU and ICU/F patients (cluster 3) while APOA2, APOD, APOH, APOM and the HDL-associated PON1 protein appear to be decreased mainly in COVID-19 non-ICU patients (cluster 7)." (PMID 36348270, 2022).
diabetes (11 papers, 2014 to 2025). "In the present and previous studies, we suggested that the blood concentration of apoA2-ATQ/AT is associated with not only early-stage PDAC, but also IPMN with a high-risk phenotype for pancreatic cancer and diabetes mellitus." (PMID 38261000, 2024). "Genetics are heavily linked to the susceptibility of T2D and the comparison of the NZO and B6-ob/ob genomes lead to the identification of several diabetes genes like Lefty1, Apoa2, Pcp4l1 and others." (PMID 34445304, 2021). "In summary, our data indicate that Lefty1, Apoa2, Pcp4l1 and Ifi202b modify beta-cell proliferation, and suggest that the alteration of their expression contributes to the development of severe diabetes in the NZO mouse strain." (PMID 26348837, 2015). "Well-known risk factors for PC, including smoking, drinking alcohol, diabetes and high body mass index (BMI), were found to be independent of the plasma apoA2-ATQ/AT level." (PMID 32937962, 2020). "This investigation with aimed the effect of APOA2–265 T > C polymorphism and dietary acid load (DAL) as either potential renal acid load (PRAL) and net endogenous acid production (NEAP) intake interaction on metabolic markers in type 2 diabetes mellitus (T2DM)." (PMID 35883173, 2022). "Also, a previous study has shown that APOA2 is upregulated in the tears of patients with diabetes." (PMID 35216421, 2022).
hypertriglyceridemia (11 papers, 2010 to 2024). A laboratory test result indicating elevated triglyceride concentration in the blood. "A recent study also shows that high levels of both apoE and apoA2 were strongly inversely associated with the ability of lipoprotein lipase to hydrolyze TG in plasma—the process which plays a key role in hypertriglyceridemia development." (PMID 35745122, 2022). "The QTL interval linked to hypercholesterolemia and hypertriglyceridemia on distal Chr 1 contains Apoa2 gene." (PMID 21167066, 2010). "Its results indicated that APOA2 rs5082 may decrease the risk of cardiovascular disease due to the lower level of postprandial hypertriglyceridemia." (PMID 26590203, 2016). "Apoa2 gene maps to the distal region of mouse Chr 1, near the Chr 1 QTL linked to hypercholesterolemia and hypertriglyceridemia in the F2 mice." (PMID 21167066, 2010). "Polymorphisms in Apoa2 gene are suggested to be responsible for the Chr 1 QTL linked to hypercholesterolemia and hypertriglyceridemia." (PMID 21167066, 2010). "APOE was identified to be essential for TG-modulating, and three genes APOA1, APOA2, and APOE were reported to be associated with hypertriglyceridemia, which may increase the risk of acute pancreatitis." (PMID 31467879, 2019). "In addition, we analyzed the frequencies of 10 variant alleles in APOA1, APOA2, APOA4, and APOA5 that have been consistently linked to hypertriglyceridemia and elevated risks of CAD." (PMID 30076208, 2018).
gastric cancer (9 papers, 2019 to 2024). A primary or metastatic malignant neoplasm involving the stomach. "The APOA2 gene is highly expressed in gastric cancers with high Claudin-6 levels, affecting cholesterol metabolism." (PMID 38067270, 2023). "APOA2 can also be used as a prognostic indicator for gastric cancers high in Clau-din-6." (PMID 38067270, 2023). "In one study, it was shown that APOA2, APOC1, and fibrinogen a-chain were distinguishing biomarkers that could diagnose gastric cancer." (PMID 38067270, 2023). "Low expression of apolipoproteins including APOA1, APOA2, APOA4 and APOC3 in plasma exosomes of patients with hepatic-specific metastasis indicated an impaired function of lipid metabolism, which could participate in hepatic metastasis in gastric cancer cells." (PMID 37568802, 2023). "However, APOA2, NTRK2, and FGA are oncogenes in PDAC, glioblastoma, and gastric cancer." (PMID 31143705, 2019).
Hypercholesterolemia (9 papers, 2010 to 2025). An increased concentration of cholesterol in the blood. "The same polymorphism of Apoa2 gene was revealed in TH strain, suggesting Apoa2 as the candidate gene underlying the Chr 1 QTL linked to hypercholesterolemia." (PMID 21167066, 2010). "For instance, a GWAS study conducted on outbred Mus stocks for variability in high density lipoprotein and hypercholesterolemia produced a linked interval of less than 100 kb, which lead to the identification of allelic differences in Apoa2 associated with hypercholesterolemia." (PMID 32912160, 2020). "APOA2 is associated with Hypercholesterolemia, Familial and Aapoaii Amyloidosis." (PMID 29567976, 2018).
prostate carcinoma (9 papers, 2010 to 2024). A carcinoma that arises from epithelial cells of the prostate gland. "Similarly, APOA2 was proven to be overexpressed in prostate cancer, specifically the 8.9-kDa isoform of APOA2." (PMID 38067270, 2023). "It has been previously suggested that APOA2 can be used as a biomarker in HCC and in prostate cancer." (PMID 36286037, 2022).
type 2 diabetes (9 papers, 2009 to 2023). "In fact SNPs in human APOA2 were shown to associate with type 2 diabetes in a Utah case-control sample." (PMID 26348837, 2015). "APOA2 is a positional and biological candidate gene for type 2 diabetes at the chromosome 1q21-q24 susceptibility locus." (PMID 19216768, 2009). "The aim of this study was to examine if HapMap phase II tag SNPs in APOA2 are associated with type 2 diabetes and quantitative traits in French Caucasian subjects." (PMID 19216768, 2009). "The APOA2 gene appeared to be a highly plausible candidate gene for type 2 diabetes susceptibility." (PMID 19216768, 2009). "However, we cannot rule out the possibilities that distal common variants or rare APOA2 variants may be associated with type 2 diabetes." (PMID 19216768, 2009). "Transgenic mice overexpressing human APOA2 on a standard chow diet displayed lipid profiles similar to that seen in human type 2 diabetes." (PMID 19216768, 2009). "We genotyped the three HapMap phase II tagging SNPs (rs6413453, rs5085 and rs5082) required to capture the common variation spanning the APOA2 locus in our type 2 diabetes case-control cohort comprising 3,093 French Caucasian subjects." (PMID 19216768, 2009). "None of the APOA2 tag SNPs were associated with type 2 diabetes in the French Caucasian case-control cohort (rs6413453, P = 0.619; rs5085, P = 0.245; rs5082, P = 0.591)." (PMID 19216768, 2009). "The available data does not support a role for common variants in APOA2 on type 2 diabetes susceptibility or related quantitative traits in Northern Europeans." (PMID 19216768, 2009). "Apoa2 variants does not link with type 2 diabetes susceptibility." (PMID 32733872, 2020). "Meta-analysis combining publicly available data with our current study confirmed in over 12,000 subjects that none of the APOA2 tag SNPs were associated with type 2 diabetes and there appeared to be no study heterogeneity (Cochran's Q: P > 0.72; I2 = 0% for all variants)." (PMID 19216768, 2009).
bladder cancer (8 papers, 2016 to 2023). "Researchers synthesized a novel bladder cancer biosensor based on polycrystalline silicon nanowire field effect transistor (Poly-SiNW-FET) for the quantification of apolipoprotein A II protein (APOA2) in urine." (PMID 35720013, 2022). "Urinary quantification of APOA2 protein was decscribed, which is a biomarker for the diagnosis of bladder cancer, and APOA2 had higher expression in liver tissues, which differ from our study, consider cell heterogeneity." (PMID 32518711, 2020). "The same research group found that the urinary APOA1 and APOA2 levels in bladder cancer samples were higher than the levels established in control samples." (PMID 30544619, 2018). "Two independent studies report elevated levels of urinary APOA1 and APOA2 in bladder cancer." (PMID 27119500, 2016). "Circulating urine levels of APOA1, APOA2, APOB, APOC2, APOC3, and APOE were elevated in bladder cancer relative to healthy controls." (PMID 28410618, 2017). "Several independent studies support the utility of circulating AQ1 and APOA1/APOA2 as non-invasive markers for RCC and bladder cancer, respectively." (PMID 28410618, 2017). "The authors report elevated levels of SAA4, ProEGF, and six apolipoproteins (APOA1, APOA2, APOB, APOC2, APOC3, and APOE) in patients with bladder cancer." (PMID 27119500, 2016). "The authors verified a panel of six proteins (AFM, ADIPOQ, C4A, APOA2, CP, and F2) that could discriminate bladder cancer from non-cancerous subjects." (PMID 27119500, 2016).
hepatocellular carcinoma (8 papers, 2013 to 2025). A malignant tumor that arises from hepatocytes. "Genes associated with lipid metabolism, such as APOA2, APOC3, APOC1, and APOE, were significantly upregulated in multiple cell types of hepatocellular carcinoma, indicating enhanced lipid metabolic activities." (PMID 39944086, 2025).
Insulin resistance (8 papers, 2010 to 2025). Increased resistance towards insulin, that is, diminished effectiveness of insulin in reducing blood glucose levels. "The association of APOA2 variants with diabetes, obesity, and insulin resistance has been reported in the previous studies; nevertheless, no such an association has been found for the HDL-C level." (PMID 26590203, 2016). "Controlling fat intake would modulate the rs9939609 polymorphism and could also help to reduce the effect of this macronutrient on other genetic variants related to metabolic alterations, such as the rs5082 polymorphism of the APOA2 gene and its influence on insulin resistance." (PMID 34208143, 2021). "Recent research has discovered a substantial link between Apoa2 and lipid metabolism as well as insulin resistance." (PMID 36242090, 2022). "Apoa2 and insulin resistance are negatively correlated in both animal and human studies." (PMID 36242090, 2022). "Furthermore, it has been suggested that the disorders of APOA2 metabolism could increase the risk of CAD by direct or indirect effects on serum lipids, insulin resistance, and atherosclerosis." (PMID 26590203, 2016).
coronary heart disease (7 papers, 2019 to 2024). "A previous study reported that APOA2 deficiency has a minor influence on lipid and lipoprotein profiles or on the occurrence of coronary heart disease in human." (PMID 32120838, 2020). "Similarly to APOA2-related pathways, diseases associated with APOC3 include apolipoprotein C-III deficiency and coronary heart disease." (PMID 39062058, 2024). "Another study showed that APOA2 rs3813627 SNP was significantly different between participants with low and high HDL levels participants, and this SNP was identified as a susceptibility allele for low HDL-c and coronary heart disease risk." (PMID 32120838, 2020).